RNU6-1045P (RNA, U6 small nuclear 1045, pseudogene)
Gene: Small nuclear RNA gene on chromosome 2 (191,370,938 to 191,371,044, forward strand). Ensembl gene ENSG00000252130.
Homologues: Orthologues: chimpanzee U6 (88% identical), macaque U6 (82% identical), dog U6 (67% identical), mouse Gm25792 (65% identical), rabbit U6 (62% identical), guinea pig U6 (57% identical), rat LOC120103222 (54% identical). Paralogues in human: RNU6-338P (75% identical), RNU6-1316P (74% identical), RNU6-664P (74% identical), RNU6-698P (74% identical), RNU6-1125P (73% identical), RNU6-1145P (73% identical), RNU6-116P (73% identical), RNU6-38P (73% identical), RNU6-46P (73% identical), RNU6-480P (73% identical), RNU6-658P (73% identical), RNU6-891P (73% identical), and 1285 more.